YBX1 (Y-box binding protein 1)
Diseases named in the same sentence as YBX1 in open-access papers (continued):
Sharing a sentence is not in itself a finding about the gene and the disease.
adenocarcinoma (2 papers, 2016 to 2025). A common cancer characterized by the presence of malignant glandular cells. "More interestingly, the patients with MIA, a less aggressive subtype of adenocarcinoma, had neither YBX1 nor CDC25a high expression in accordance with IASLC/ATS/ERS international multidisciplinary classification." (PMID 27384875, 2016).
cardiovascular disease (2 papers, 2023 to 2025). "In summary, we highlight the important functions of YBX1 in IH and identified the potential downstream targets of YBX1, which can be used as candidate therapeutic targets for IH and other cardiovascular diseases in the future." (PMID 40045484, 2025). "Recently, various studies have shown that YBX1 plays an important role in cardiovascular disease." (PMID 37253771, 2023).
GI tumours (2 papers, 2015 to 2025). "Further, YBX1 (YB1), another pro-oncogenic RBP, is associated with poor prognosis of GI tumours." (PMID 39718205, 2025).
neurodegenerative disease (2 papers, 2022 to 2024). A disorder of the central nervous system characterized by gradual and progressive loss of neural tissue and neurologic function. "There are many reports that YBX1 is associated with neurodegenerative disease." (PMID 38255791, 2024). "Moreover, the emerging role of YBX1 as a neural input is also proposed where the high level of YBX1 was strongly associated with nerve cancer and neurodegenerative diseases." (PMID 38255791, 2024). "The age-related cyclic formation and dissolution of stress granules in neurons, which are regulated by YBX1 and G3BP1, may contribute to protein aggregation, a hallmark of neurodegenerative diseases." (PMID 38255791, 2024).
YBX1 also shares sentences with these, for which no sentence is quoted: stomach cancer (8 papers); diabetic cardiomyopathy (5); pancreatic adenocarcinoma (4); Alzheimer disease (3); colitis (3); endometriosis (3); invasive breast carcinoma (3); metabolic disease (3); prostate tumor (3); renal fibrosis (3); synovial sarcoma (3); adrenocortical carcinoma (2); Arthritis (2); autism (2); bone metastasis (2); brain cancer (2); dyslipidemia (2); HIV-1 infection (2); infarction (2); invasive ductal carcinomas (2); ischemic cardiomyopathy (2); kidney damage (2); kidney disease (2); Lyme disease (2); metastatic melanoma (2); ovarian tumor (2); preeclampsia (2); prostate adenocarcinoma (2); spinal chordoma (2); systemic sclerosis (2).
A further 92 diseases each share a sentence with YBX1 in 2 papers or fewer.